KLK10 (kallikrein related peptidase 10)
Diseases named in the same sentence as KLK10 in open-access papers (continued):
Sharing a sentence is not in itself a finding about the gene and the disease.
Cirrhosis (1 paper, 2014). A chronic disorder of the liver in which liver tissue becomes scarred and is partially replaced by regenerative nodules and fibrotic tissue resulting in loss of liver function. "Using Methylation specific PCR (MSP) method, they validated the methylation status of KLK10 and OXGR1 in tumors, and found that hypermethylation of KLK10 was associated with Hepatitis C virus (HCV) infection and cirrhosis." (PMID 24635883, 2014).
clear cell renal cell carcinoma (1 paper, 2018). "Renal clear cell carcinoma had six KLKs in which increased expression was associated with overall survival (KLK2: HR = 1.69; KLK4: HR = 1.63; KLK8: HR = 1.71; KLK10: HR = 2.12; KLK11: HR = 1.76; and KLK14: HR = 1.86)." (PMID 29707153, 2018).
corticotroph adenomas (1 paper, 2023). "Regarding human pituitary tumors, KLK10 has been found to be consistently expressed in prolactinomas, thyrotropinomas, somatotrophinomas and corticotroph adenomas." (PMID 37033229, 2023).
Familial adenomatous polyposis (1 paper, 2018). Familial adenomatous polyposis (FAP) is characterized by the development of hundreds to thousands of adenomas in the rectum and colon during the second decade of life. "Indeed, we have observed increased methylation in the promoters of several tumor suppressor genes including APC, a well-characterized tumor suppressor gene associated with familial adenomatous polyposis, and KLK10, which has been shown to repress proliferation and induce apoptosis in PCa cells." (PMID 29740534, 2018).
gastric tumor (1 paper, 2017). "The GC cohort was also divided into 2 groups according to pathological KLK10 expression (pKLK10) in primary gastric tumor tissues: the low pKLK10 group had an immunostaining score of 0-2 while the high pKLK10 group had an immunostaining score of 3-7." (PMID 28418926, 2017).
hypospadias (1 paper, 2020). Hypospadias is the displacement of the urethral meatus on the ventrum of the penis. "This region on chromosome 19 is characterized by clusters of sialic acid-binding Ig-like lectin (SIGLEC) and kallikrein (KLK) genes, among which we identified likely causal relationships with hypospadias (CD33/SIGLEC3, SIGLEC5, SIGLEC7, KLK5, KLK7, KLK10, KLK13, and KLK14)." (PMID 32728162, 2020).
mucoepidermoid carcinoma (1 paper, 2016). A carcinoma morphologically characterized the presence of cuboidal mucous cells, goblet-like mucous cells, squamoid cells, cystic changes, and a fibrotic stromal formation. "Neither of the mucoepidermoid carcinoma showed a significant alteration in the immunoreactive scores of KLK10 in comparison with the normal salivary gland tissues." (PMID 28855925, 2016). "In our` study, the ductal cell structures showed higher staining intensity for KLK10 than non-ductal cells in normal tissue and in pleomorphic adenomas and mucoepidermoid carcinoma, ductal cells were stained more intensely than non-ductal cells and the difference was significant." (PMID 28855925, 2016).
ovarian tumors (1 paper, 2018). "In the present study we investigate the possible role of KLK10 exon 3 methylation in ovarian tumor diagnosis and prognosis." (PMID 29690914, 2018). "In the present study, KLK10 exon 3 methylation is assessed for its possible role in the biology, diagnosis and/or prognosis of ovarian tumors." (PMID 29690914, 2018). "In the literature we could find only one study on KLK10 exon 3 methyaltion in primary ovarian tumors that was reported by Sidiropoulos and colleagues." (PMID 29690914, 2018).
papillary thyroid cancer (1 paper, 2025). "Earlier studies have indicated that KLK7, KLK10, and KLK11 are linked to the survival rates and immune reactions of individuals with papillary thyroid cancer (PTC)." (PMID 39991575, 2025).
pituitary tumor (1 paper, 2023). A benign or malignant neoplasm affecting the pituitary gland. "Moreover, drugs specifically designed to target KLK10 and PEBP1 would be welcome, and would be useful for pituitary tumors currently lacking an efficient medical treatment." (PMID 37033229, 2023).
prostate tumor (1 paper, 2015). "A recent study showed that CpG methylation of KLK10 was higher in prostate tumor compared to normal tissue and also reported an association between DNA methylation and clinicopathological parameters." (PMID 26692910, 2015).
renal cell carcinoma (1 paper, 2022). "In renal cell carcinoma, the luciferase assay method demonstrated that let-7f targets the KLK10, a subgroup of the Kallikreins family that is expressed in various normal organs such as breast, testis, ovary, kidney, and prostate with a diverse set of physiological functions." (PMID 35488374, 2022).
ulcerative colitis (1 paper, 2015). An inflammatory bowel disease involving the mucosal surface of the large intestine and rectum. "In this study, the expression pattern of the Klk10 transcript was similar to that of the colonic muscle in patients with ulcerative colitis, even though their increase ratios differed between the two groups." (PMID 26151867, 2015).
uterine cancer (1 paper, 2022). Primary or metastatic malignant neoplasm involving the uterine corpus and/or the cervix. "Further studies, however, showed a more complex story as KLK10 is overexpressed in ovarian, pancreatic, and uterine cancer." (PMID 35014606, 2022).
tumor (71 papers, 2001 to 2026). "In cancer biology, KLK10 has been associated with both tumor-suppressive and tumor-promoting roles, depending on the cellular context." (PMID 41516101, 2025). "Of the 8 previous studies described earlier in this Discussion, 5 reported that high expression of KLK10 in tumor tissue is associated with advanced stage or poor prognosis, which supports our findings." (PMID 28418926, 2017). "Moreover, patients with high KLK10 expression were associated with a hot tumor immune microenvironment, poorer immune checkpoint blocking treatment, and shorter survival." (PMID 37938164, 2023). "Moreover, the TIDE analysis implied that patients with high KLK10 expression were more susceptible to tumor immune escape, in accordance with previous studies." (PMID 37938164, 2023). "Among them, urinary kallikrein 10 (KLK10) was positively associated with tumor stage progression." (PMID 28418926, 2017). "Klk10 encodes serine proteases, including a member of the human tissue kallikrein family, and may play a role as a tumor suppressor gene to inhibit tumor formation in nude mice." (PMID 26151867, 2015). "High levels of KLK10 in the serum are associated with advanced stage serous tumours with large residual disease and poor response to chemotherapy, while low levels of KLK10 in the tumour predict poor overall survival." (PMID 22102857, 2011). "Furthermore, KLK10-derived peptides have been identified in both HLA class I and class II complexes in ovarian cancer, underscoring their immunogenic potential and relevance as a source of tumor-associated antigens." (PMID 41516101, 2025). "Finally these findings support the hypothesis that KLK10 is a tumour suppressor and further underline the involvement of KLK5, 6 and 10 in ovarian pathophysiology." (PMID 22102857, 2011). "On the other hand, in the presence of oncogenic KRAS, KLK10 promotes tumor progression through the PAR1/PDK1/Akt axis, and it has also been linked to epithelial–mesenchymal transition via activation of the FAK/SRC/ERK pathway." (PMID 41516101, 2025). "KLK10 is expressed in both neuronal and glial compartments and is thought to influence neuroinflammatory regulation and tumor microenvironment remodeling." (PMID 41516101, 2025). "Single-cell and spatial analyses revealed cellular specificity (e.g., IFI27/KLK10 in ductal cells/fibroblasts) and tumor-region-specific expression patterns." (PMID 41008826, 2025). "For example, KLK10 modulates tumor growth and glucose metabolism in CRC through the PI3K/Akt/mTOR pathway." (PMID 38585643, 2024). "Amongst the differentially expressed EMT genes from that study, we find overlap with PTPRK-regulated genes including TGFB1, COL6A1, GPX3 and KLK10, as well as genes encoding LSR and PKP2, both of which are hyperphosphorylated in PTPRK KO tumours." (PMID 38904097, 2024). "Collectively, these results highlight the pro-tumor effects of KLK10 in CRC, in accordance with the results of bioinformatics analysis." (PMID 37938164, 2023). "The results indicated that high KLK10 expression was positively correlated with the tumor immune escape (T cell dysfunction and T cell exclusion), which provides novel insights into precision immunotherapy in CRC." (PMID 37938164, 2023). "In contrast, several studies concluded that KLK10 is a tumor suppressor gene, which is a major modulator of inhibition of vascular cell proliferation and migration." (PMID 36818914, 2022). "First, the relative expression levels of KLK10 and KLK11 mRNA were analyzed with respect to their association with established clinical variables, including age, lymph node status, and tumor size." (PMID 36294951, 2022). "Mouse models of SCAs and in vitro studies showed a reduced expression of tumor suppressor genes RB1 and KLK10, and altered expression of other genes related to tumor progression and metastasis." (PMID 35743266, 2022).
tumor (continued). "While the tumour-biological role of KLK10 in PDAC was assessed by gene silencing and a cell migration assay, the role of KLK6 was not further investigated." (PMID 34439122, 2021). "Although KLK8 and KLK10 overexpression in OSCC and other cancers have been associated with tumor aggressiveness and overall prognosis, their precise mechanisms of activity are yet to be clearly deciphered." (PMID 32630820, 2020). "In this study, KLK7 and KLK10 were identified as the biomarkers of tumor stage and prognosis of PTC, which were consistent with the previous report." (PMID 30414611, 2018). "Noteworthy is that overexpression of KLK10 was found in malignant sample subsets (tissues or sera) in cancer types in which KLK10 was shown experimentally as tumor suppressor; breast, prostate, gastric and ovary." (PMID 29690914, 2018). "On one hand, KLK10 has been proposed to act as tumor suppressor in various types of human cancer, such as breast, esophageal, prostate, testicular, and tongue cancer." (PMID 29095848, 2017). "Immunohistochemical analyses also demonstrated a positive correlation between tumor stage and KLK10 expression in GC tissues (r=0.426, P<0.001)." (PMID 28418926, 2017). "The non-invasive assessment approach 18F-FLT micro PET/CT showed the lower proliferation metabolism of KLK10-over-expressing PC3 tumour tissue with the lower uptake of 18F-FLT." (PMID 26616394, 2015). "Over-expression of KLK10 in ES2 EOC cells reduced their anchorage-independent growth in vitro and caused a smaller tumor burden in an animal model compared to vector controls." (PMID 24043563, 2014). "Adding recombinant KLK10 protein into cultures confirmed these findings, supporting its role as a tumor suppressor in EOC progression both in vitro and in vivo." (PMID 24043563, 2014). "The recombinant KLK10 doses injected IP lead to plasma concentrations orders of magnitude higher at one hour than the highest doses recorded in KLK10 tumour-bearing mice, albeit transiently." (PMID 22102857, 2011). "The molecular pathway by which the catalytically inactive KLK10 exerts its biological effects remains elusive, despite the accumulating evidence of its tumour-suppressing qualities." (PMID 22102857, 2011). "Probably future studies including more patients can prove a use for KLK6 or KLK10 as tumour biomarkers in PDAC." (PMID 18854834, 2008). "Beyond influencing tumor growth, KLK10 has emerged as a critical mediator of drug resistance." (PMID 41516101, 2025). "In non-small cell lung cancer (NSCLC) KLK10 was found to act as a functional tumor suppressor gene, and epigenetic inactivation of KLK10 is a common event contributing to NSCLC pathogenesis and, therefore, may be used as a potential biomarker." (PMID 34792145, 2022). "obtained a high-purity KLK10-expressed stable cell line PC3-KLK10 by reconstructed lentiviral vector, and they found that over-expressing KLK10 in PC3 could decrease tumor proliferation and increase apoptosis and inhibit glucose metabolism at the same time." (PMID 35756667, 2022). "KLK10 is downregulated in breast, prostate, and other cancers functioning as a tumor suppressor." (PMID 31612115, 2019). "Moreover, KLK10 exon 3 unmethylated PCR product concentration mean ± SD (ng/μl) showed statistically significant differences in tumor and normal samples in the two patient groups." (PMID 29690914, 2018). "At the functional aspect, the reported antitumor role of KLK10 was demonstrated in vector-mediated transfection experiments in vitro and/or in tumor xenograft in mice using different cancer cell lines; e.g. breast, prostate and gastric cell, including ovarian cell line." (PMID 29690914, 2018). "In vitro and in vivo assays showed that over-expressing KLK10 in PC3 could decelerate tumour proliferation, which was accompanied with an increase in apoptosis and suppression of glucose metabolism." (PMID 26616394, 2015).
tumor (continued). "The exogenous over-expression of KLK10 in PC3 cells could decelerate tumour proliferation, which is accompanied by apoptosis induction and glucose metabolism reduction." (PMID 26616394, 2015). "Similarly, patients with tumours of each subtype have detectable levels of KLK10 in their cytosols, with a slight but significantly higher proportion of KLK10 high patients being of the serous subtype." (PMID 22102857, 2011). "Immunohistochemistry in native tumour tissue could prove not only an intense expression for KLK10 in 64.4% of the malignant cells, but also for KLK6 in 91.5%." (PMID 18854834, 2008). "A previous analysis of the kallikrein-related peptidase family in CRC tumor samples from the TCGA database revealed that KLK6 overexpression in human tumors is associated with the overexpression of other members of the kallikreins protease family, i.e., KLK7, KLK8, and KLK10." (PMID 39594797, 2024). "In addition to the actual tumor-promoting properties of KLK10/11-triggered effects, there might be also implications towards improved therapy responses, granting them additional predictive value to both KLKs." (PMID 36294951, 2022). "Thus, our results demonstrated that KLK10 may function as a tumour suppressor by repressing proliferation, enhancing apoptosis and decreasing glucose metabolism in PC3 cells." (PMID 26616394, 2015). "So, the importance of KLK10 in tumour progression remains unclear." (PMID 18854834, 2008). "Functional studies reveal that KLK10 can activate CD4+ T cells and drive M2 macrophage polarization in colorectal cancer, thereby shaping the immune landscape in a tumor-promoting direction." (PMID 41516101, 2025). "While PCR validation on matched tumor/normal tissues confirmed significant differential expression of IFI27, KIF20A, KLK10, and TOP2A." (PMID 41008826, 2025). "IFI27, KIF20A, KLK10, and TOP2A were highly expressed in tumor cells, supporting their potential as prognostic biomarkers in PAAD." (PMID 41008826, 2025). "An examination of mRNA levels within the TCGA-GTEx cohort demonstrated a notable increase in KLK10, LAMA3, MET, KRT7, and SFTA2, alongside a decrease in MT1X in tumor samples compared to their normal counterparts." (PMID 38893622, 2024). "All in all, both KLK10 and KLK11 appear to exhibit tumor-promoting properties in some cancer entities." (PMID 36294951, 2022). "The mRNA expression levels of COL17A1, CEP55, KLK10, MET, ITGB6, ANKRD22, and ARNTL2 were significantly increased in PAAD tumor tissue." (PMID 31612115, 2019). "The downregulated MCOLN3 and SLC25A45 with HR < 1 were considered as tumor suppressors, whereas the upregulated COL17A1, CEP55, KLK10, MET, ITGB6, ANKRD22, and ARNTL2 with HR > 1 were regarded as oncogenes." (PMID 31612115, 2019). "We have previously discovered and/or characterized tumor-specific DNA methylation of six genes (APC, GSTP1, HOXD3, KLK10, TBX15, and TGFβ2) in radical prostatectomy tumor samples." (PMID 30470249, 2018). "For instance, kallikrein genes KLK5, KLK6 and KLK7 were downregulated in HPV16+ tumours and co-expressed with two overlapping antisense transcripts: CTB-147C22.8 and CTB147C22-9, as well as KLK10 with its antisense CTC-518B2.12." (PMID 29263803, 2016). "In our study, the expression of HK-2 was significantly down-regulated in KLK10-expressed PC3 cells and xenograft tumour tissue, which was consistent with the results of 18F-FDG micro PET/CT scan." (PMID 26616394, 2015). "18F-FDG micro PET/CT, which noninvasively estimates the effect of KLK10 on PC3 xenograft tumour in vivo, revealed that the uptake of 18F-FDG was lower in the PC3-KLK10 xenograft tumour than in the control group." (PMID 26616394, 2015). "Related proteins such as Bcl-2 and HK-2 were down-regulated and KLK10 was up-regulated in the PC3 cell line and xenograft tumour." (PMID 26616394, 2015). "Our study revealed that exogenously over-expressing KLK10 can decelerate the proliferation of PC3 cells and xenograft tumour." (PMID 26616394, 2015).